GPX4 (glutathione peroxidase 4)
Diseases named in the same sentence as GPX4 in open-access papers (continued):
Sharing a sentence is not in itself a finding about the gene and the disease.
thyroid cancer (continued). "However, Chen and colleagues presented opposite results, finding that increased GPX4 expression promotes thyroid cancer tumorigenesis." (PMID 40746894, 2025). "Also, GPX4 inhibition decreases the spheroid formation, cell viability, and migration of thyroid cancer cells." (PMID 38778030, 2024). "Thus, to better explain the predictive value of GPX4, we will collect clinical data and focus on the prognostic effect of GPX4 expression in thyroid cancer in the future." (PMID 36626251, 2023). "In addition, the predictive value of GPX4 in thyroid cancer was assessed by using Cox regression analysis and nomograms." (PMID 36626251, 2023). "Furthermore, we determined that GPX4 facilitates proliferation and inhibits ferroptosis in thyroid cancer cells." (PMID 36626251, 2023). "Finally, we conducted several in vitro experiments to determine the influence of GPX4 expression on proliferation and ferroptosis in thyroid cancer cells." (PMID 36626251, 2023). "Therefore, we divided 510 thyroid cancer patients into two groups according to the median value of GPX4 expression: high and low GPX4 expression groups." (PMID 36626251, 2023). "Here, we explore the effect of GPX4 on thyroid cancer tumorigenesis and prognosis." (PMID 36626251, 2023). "The clinical significance of GPX4 in thyroid cancer is another focus of attention." (PMID 36626251, 2023). "Based on ROC curve analysis, GPX4 seems to be a reliable biomarker for thyroid cancer diagnosis." (PMID 36626251, 2023). "Evidence indicates that GPX4 inhibitors have specific lethality in tumor cells through ferroptosis, but no associated research has been conducted in thyroid cancer." (PMID 36626251, 2023). "The predictive performance of GPX4 suggests that it might be regarded as a universal prognostic biomarker for thyroid cancer." (PMID 36626251, 2023). "We have also demonstrated that GPX4 is highly expressed in some thyroid cancer cell lines." (PMID 36371529, 2022). "Therefore, examining mTOR pathway suppression by targeting GPX4 can provide further mechanistic insight into mTOR pathway signaling as a potential therapeutic target for advanced thyroid cancers." (PMID 36371529, 2022). "Research shows that compared with normal tissues, GPX4's expression level in tumor tissues is significantly higher, such as colon adenocarcinoma, renal chromophobe cell, renal clear cell carcinoma, lung adenocarcinoma, prostate cancer, rectal adenocarcinoma, thyroid cancer and endometrial cancer." (PMID 38333875, 2024). "Thus, GPX4 may constitute a biomarker for thyroid cancer diagnosis and prognosis evaluation, and targeting GPX4 might be an effective treatment for thyroid cancer." (PMID 36626251, 2023). "Finally, we conducted in vitro experiments to investigate whether GPX4 expression affects proliferation and activates ferroptosis in thyroid cancer cells." (PMID 36626251, 2023). "Thus, observed potent induction of ferroptosis, GPX4-dependent novel suppression of mTOR pathway and DNA damage repair response in preclinical in vitro model of TC supports GPX4 targeting for therapeutic benefit in advanced therapy-resistant thyroid cancers." (PMID 36371529, 2022). "This analysis demonstrated that the expression levels of GPX4 and TfR1 can vary between thyroid cancer cell lines, suggesting underlying tumor heterogeneity at play, and that the GPX4 and TfR1 basal expressions may not serve as reliable markers in vitro." (PMID 36371529, 2022). "Consequently, the inhibition of GPX4 may be a promising therapeutic strategy for thyroid cancer." (PMID 40529834, 2025). "GPX4 detoxifies lipid peroxides using GSH as a cofactor, and its expression is upregulated in thyroid cancer tissues, including ATC, where it correlates with aggressive progression." (PMID 41294853, 2025).
thyroid cancer (continued). "While iron overload and lipid peroxidation are common features of ferroptosis across malignancies, the specific involvement of thyroid-specific molecules like GPX4 and SLC7A11 in regulating ferroptosis pathways in thyroid cancer is more pronounced." (PMID 39917169, 2025). "The results verified that GPX4 knockdown obviously inhibited protein expression of Ki-67 and PCNA, as well as proliferation in thyroid cancer cells." (PMID 36626251, 2023). "We identified multi-faceted effects of GPX4 inhibitor, RSL3, in suppressing thyroid cancer cell survival." (PMID 36371529, 2022). "Thus, in this review, the roles of key ferroptosis regulators, including iron, glutathione peroxidase 4 (GPX4), glutathione (GSH), and dipeptidyl-peptidase-4 (DPP4), in thyroid cancer are discussed." (PMID 40529834, 2025). "Therefore, to explore the influence of GPX4 in thyroid cancer cells, we focused our attention on FTC133 cells because of their higher expression of GPX4." (PMID 36626251, 2023). "AKR1C3, BID, FBXW7, GPX4, and MAP3K5 were independent prognosis signatures of thyroid cancer." (PMID 35741758, 2022). "Univariate cox regression analysis demonstrated that DPP4 [hazard ratio (HR): 0.756, 95% confidence interval (CI): 0.623–0.918, p = 0.004], GPX4 (HR: 0.381, 95% CI: 0.147–0.990, p = 0.048) and GSS (HR: 0.361, 95% CI: 0.139–0.935, p = 0.036) were protective factors for thyroid cancer prognosis." (PMID 33928101, 2021). "Among them, DPP4, GPX4, and GSS were protective factors for thyroid cancer prognosis." (PMID 33928101, 2021). "Glutathione peroxidase family showed variable gene expression: GPX1 and GPX2 expression analysis suggested minor increase in mRNA synthesis, GPX3, GPX5, and GPX7 expression was downregulated in thyroid cancers, whereas GPX4 expression did not change." (PMID 26664298, 2015). "Our data suggested that AKR1C1 (p < 0.0001), DPP4 (p < 0.0001), GPX4 (p = 0.0001), GSS (p < 0.0001), HMGCR (p < 0.0001), TFRC (p < 0.0001), SQLE (p = 0.0004), and PGD (p = 0.0005) were all significantly highly expressed in thyroid cancer tissues compared to normal tissues." (PMID 33928101, 2021). "In previous studies, BID, FBXW7, and GPX4 had already been found to be significant in thyroid cancer, whereas the role of AKR1C3 and MAP3K5 in the development and progression of thyroid cancer has not yet been reported." (PMID 35741758, 2022).
lupus (17 papers, 2016 to 2025). "GPX4 deficiency increases ferroptosis susceptibility, as seen in systemic lupus erythematosus, where suppressed GPX4 induces neutrophil ferroptosis." (PMID 40858533, 2025). "Neutrophils from systemic lupus erythematosus patients exhibit heightened susceptibility to ferroptosis due to suppressed expression of GPX4 compared to healthy individuals." (PMID 38844964, 2024). "Glutathione peroxidase 4 (GPX4), a key ferroptosis regulatory protein, was found to be significantly decreased in the brain in lupus." (PMID 40332005, 2025). "In lupus-prone mice with neutrophil-specific glutathione peroxidase-4 (GPX4) haploinsufficient, treatment with a specific ferroptosis inhibitor via GPX4, the component most downstream to the ferroptosis pathway, significantly ameliorated disease severity." (PMID 35958572, 2022). "A recent study filled this knowledge gap by revealing that ferroptosis induced by GPX4 transcriptional suppression represents a main form of neutrophil death in lupus." (PMID 34826064, 2022). "Neutrophils from systemic lupus erythematosus (SLE) patients exhibit ferroptosis due to the transcriptional repression of GPX4." (PMID 34960652, 2021). "Interestingly, myeloid-specific GPX4-haploinsufficient mice develop spontaneous lupus-like symptoms, whereas complete GPX4 ablation in neutrophils results in severe neutropenia without inducing lupus-like disease." (PMID 39867458, 2025). "Moreover, specific knockdown of Gpx4 in mouse neutrophils elicits clinical features resembling human systemic lupus erythematosus." (PMID 38844964, 2024). "Furthermore, GPX4 ablation in neutrophils exacerbates the development of autoimmune diseases, such as systemic lupus erythematosus, by inducing ferroptosis." (PMID 38515187, 2024). "On the other hand, systemic immune dysregulation is exemplified in systemic lupus erythematosus (SLE), where neutrophil ferroptosis synergizes with CaMKIV-CREMα pathway-mediated GPX4 suppression to potentiate NETosis." (PMID 40421132, 2025). "The deletion of the ferroptosis negative‐regulating protein GPX4 specifically in the myeloid lineage in mice can induce a typical lupus‐like phenotype." (PMID 40060194, 2025). "In Systemic Lupus Erythematosus (SLE), IFN-α inhibits GPx4 expression through CREMα induction, promoting ferroptosis of neutrophils and resulting in neutropenia." (PMID 41462611, 2025). "Mice with neutrophil‐specific GPX4 haploinsufficiency recapitulate the key clinical features of human SLE, and treatment with ferroptosis inhibitors substantially reduces disease severity in lupus‐prone mice, underscoring the role of neutrophil ferroptosis in lupus pathogenesis." (PMID 38044275, 2024).
osteoporosis (17 papers, 2022 to 2026). A condition of reduced bone mass, with decreased cortical thickness and a decrease in the number and size of the trabeculae of cancellous bone (but normal chemical composition), resulting in increased fracture incidence. "Recent studies have reported that DNMT abnormalities induce epigenetic suppression of GPX4, which subsequently triggers osteoblast ferroptosis, which is a key mechanism underlying osteoporosis." (PMID 41551515, 2025). "Deferoxamine (DFO), a well-known iron chelator, has been shown to attenuate osteoporosis by modulating the expression of key ferroptosis-related proteins such as GPX4, HMOX1, and SLC7A11 in osteoblasts." (PMID 40906362, 2025). "Studies have shown that PAC has certain potential in alleviating osteoporosis through the SIRT6/Nrf2/GPX4 pathway." (PMID 41551515, 2025). "In patients with type II diabetes and osteoporosis, reduced GPX4 expression has been observed, suggesting increased susceptibility of bone cells to ferroptosis." (PMID 40906362, 2025). "Conversely, effectively reducing the RANKL/OPG ratio, increasing the expression of GPX4, and inhibiting the ferroptosis pathway can thereby treat osteoporosis." (PMID 41551515, 2025). "Among absorbable components in AA, mangiferin has acted as a ferroptosis inhibitor through the Keap1/Nrf2/SLC7A11/GPX4 pathway in osteoporosis mice." (PMID 39512823, 2024). "Conversely, DNMT inhibition with SGI-1027 reversed promoter hypermethylation, GPX4 suppression and ferroptotic osteoporosis." (PMID 39617773, 2024). "Our previous work revealed that activation of the SLC7A11/GPX4 signaling pathway inhibits the onset of ferroptosis, and eventually attenuates osteoporosis." (PMID 39512823, 2024). "Importantly, GPX4 is a major downstream effector of GC signaling pathway, and during GC-induced osteoporosis, GC mediates its osteoclastogenesis effects by inhibiting GPX4 expression." (PMID 40180675, 2025). "To directly test the role of osteoblast Gpx4 suppression in ferroptotic osteoporosis, we generated a strain of osteoblast-specific Gpx4 knockout mice by crossing Gpx4fl/fl mice with Col1a1-Cre mice, supposedly resulting in the deletion of exons 2–4 of the Gpx4 gene in osteoblasts." (PMID 39617773, 2024). "Depletion of GSH and decreased GPX4 activity can lead to ferroptosis and induce osteoporosis." (PMID 35844870, 2022). "In osteoporosis caused by corticosteroids, ferroptosis‐associated proteins, prostaglandin‐endoperoxide synthase 2 (PTGS2), and Acyl‐CoA synthetase long‐chain family member 4 (ACSL4) levels were upregulated, while glutathione peroxidase 4 (GPX4) levels were decreased." (PMID 37622525, 2023). "A study on osteoporosis showed that the transcription factor YAP1 directly binds to and upregulates GPX4 transcriptional activity, thereby inhibiting osteoblast ferroptosis and promoting bone formation." (PMID 41480314, 2025). "And the key proteins discovered from animal models, such as GPX4, SLC7A11, ACSL4, etc., are extremely difficult and unethical to obtain from healthy human bodies, especially in early bone tissue samples of osteoporosis." (PMID 41551515, 2025). "Alterations in the expression of ferroptosis biomarkers, such as GPX4, SLC7A11, and SLC3A2, have been observed in the steroid-induced osteoporosis context." (PMID 36854703, 2023). "The Eucommia-Dipsacus herb pair enhances serum estradiol levels, as well as GPX4 and FTH1 protein levels in ovariectomized osteoporotic rats, inhibits femoral ferroptosis, and consequently increases femoral bone mineral density, alleviating osteoporosis." (PMID 41551515, 2025).
osteoporosis (continued). "Deng found that the expression of METTL14 was decreased in postmenopausal patients with osteoporosis, and overexpression of METTL14 could stabilize GPX4 mRNA and inhibit osteoclast differentiation and bone absorption." (PMID 40051055, 2025). "Although not rigorous enough, many animal model studies, including those on osteoporosis, TBI, and spinal cord injury, regard the lack of GPx4 as the landmark of ferroptosis." (PMID 35186185, 2022).
pulmonary fibrosis (17 papers, 2020 to 2026). Chronic progressive interstitial lung disorder characterized by the replacement of the lung tissue by connective tissue, leading to progressive dyspnea, respiratory failure, or right heart failure. "As a ferroptosis activator, RSL3 can cause the occurrence of cellular ferroptosis and idiopathic pulmonary fibrosis by directly inhibiting GPX4, which is associated with the redox imbalance in the lung." (PMID 36672671, 2023). "In addition, iron overload may cause lung fibrosis according to increased lipid peroxidation and decreased glutathione peroxidase 4 (GPX4) activity in lung tissues." (PMID 34983465, 2022). "In idiopathic pulmonary fibrosis, GPX4 levels in pulmonary fibroblasts are reduced, and GPX4 knockdown significantly enhances TGF-β-induced SMAD2/3 activation, thereby promoting myofibroblast differentiation in lung fibroblasts." (PMID 40001138, 2025). "While the finding of ferroptosis is closely related to pulmonary fibrosis, it plays a key role in the pathogenesis of pulmonary fibrosis with iron overload, ROS accumulation, lipid peroxidation, and inhibition of GPX4 activity." (PMID 38562175, 2024). "Liproxstatin-1, an ferroptosis inhibitor, delayed fibroblast differentiation into myofibroblasts and reduced pulmonary fibrosis by limiting collagen deposition and decreasing GPX4 expression." (PMID 38562175, 2024). "The expression of GPX4 was decreased in bleomycin-induced pulmonary fibrosis in mice, and the fibrosis was more severe when GPX4 gene was knocked out." (PMID 36672671, 2023). "It has been reported that the genetic downregulation of glutathione peroxidase 4 (GPX4) expression exacerbates BLM-induced lung fibrosis." (PMID 34204949, 2021). "Reduced expression of GPx4 and increased 4-hydroxynonenal immunostaining was seen in IPF lungs, and genetic deletion of GPx4 (Gpx4+/−) mice showed enhanced bleomycin-induced lung fibrosis and TGF-β-mediated myofibroblast differentiation in vitro." (PMID 32549377, 2020). "Together, these findings show that AT2 cell specific YY1 knockdown re-establishes antioxidant and iron homeostasis, limits GPX4-dependent ferroptosis, and markedly attenuates PS-NPs-induced pulmonary fibrosis, supporting YY1 as a potential therapeutic target in nanoplastic-related lung injury." (PMID 41560817, 2026). "Ferroptosis and GPX4 are closely related to infectious diseases such as pneumonia and pulmonary fibrosis, which may be an important factor leading to oxidative stress injury." (PMID 41509128, 2026). "Therefore, GPX4 regulation of pulmonary fibrosis induced by bleomycin in mice can be attributed to changes in ferroptosis." (PMID 36672671, 2023). "As such, the expression of GPX4 is decreased in lung tissue of idiopathic pulmonary fibrosis." (PMID 36672671, 2023). "Therefore, it is speculated that GPX4 mediates Oroxylin A‐improved pulmonary fibrosis of RP through the induction of Nrf2." (PMID 41509128, 2026). "Considering that GPX4 evokes a countereffect on phospholipid (PL) peroxidation, ferroptosis, defined as a PL peroxidation-induced sudden cell death, may be involved in the development of lung fibrosis." (PMID 34204949, 2021). "The markers GPX4 and SLC7A11, which typically decrease during ferroptosis activation, were found significantly reduced in pulmonary fibrosis mice (P < 0.01)." (PMID 38584671, 2024). "When GPX4 is downregulated, TGF-β can induce fibroblast differentiation in vitro and generate pulmonary fibrosis." (PMID 36672671, 2023). "Notably, ferroptosis-related heterozygous gene GPX4 flawed mice showed more severe bleomycin-induced pulmonary fibrosis, while this effect was attenuated in transgenic mice, indicating that ferroptosis may be substantially contributing to the pulmonary fibrosis." (PMID 35069688, 2021). "Interestingly, APD downregulates ACSL4, PTGS2, and ROS while upregulating GPX4 and SLC7A11, indicating its role in inhibiting ferroptosis in pulmonary fibrosis." (PMID 38584671, 2024).
pulmonary fibrosis (continued). "This study first, to our knowledge, identified the involvement of Uhrf1 in mediating the ferroptosis of chemically injured AEC2s via de novo promoter-specific methylation of both GPX4 and FSP1 genes, which consequently accelerates the process of pulmonary fibrosis." (PMID 36566325, 2022).